MMP1 (matrix metallopeptidase 1)
Diseases named in the same sentence as MMP1 in open-access papers (continued):
Sharing a sentence is not in itself a finding about the gene and the disease.
cancer (continued). "Importantly, we clarified the pivotal role of HAS2, which probably led to disruption in the expression of MMP1 and TIMP1 and consequently promoted cancer progression." (PMID 27884164, 2016). "p38α also induces the expression of MMP1, MMP2, MMP9 and MMP13 in other types of cancer." (PMID 27286263, 2016). "MMP-1 and MMP-13 should continue to be looked upon as targets in cancer and COPD therapy." (PMID 25664615, 2015). "Among these anti-cancer targets, 3-phosphoinositide-dependent protein kinase-1(PDPK1), MMP1, MMP2, MMP3, nitric oxide synthase (NOS2), and inosine-5′-monophosphate dehydrogenase 2 (IMPDH2) showed similar binding affinity with bruceantin as that of some marketing drugs." (PMID 24429698, 2014). "According to previous reports, p-STAT3 could interact with p-c-Jun to regulate MMP-1, MMP-7 or other genes expression in human cancers." (PMID 25070240, 2014). "Interestingly only 6 genes including CCDC19, MMP1, SLC family, TEKT2, WDR family and ZMYND10 had been reported relevant to cancer survival in a separate study (where a total of 88 genes were reported,)." (PMID 25551281, 2014). "In another case with early HCC, well-differentiated HCC cells positive for MMP-1 protein were compressed by moderately differentiated cancer cells which were negative for MMP-1 staining." (PMID 24978432, 2014). "In addition to MMP12 (present study), MMP1, MMP13 and MMP28 have also been shown to promote invasion and metastasis in various cancers." (PMID 24885469, 2014). "Using pharmacological inhibitors, siRNAs, and blocking antibodies, we demonstrated that the MMP-1 and MMP-2 matrix metalloproteinases, known to participate in late stages of cancer invasion and metastasis, are responsible for this enhancement of early migratory capacity." (PMID 23675494, 2013). "Reducing M2 macrophage characteristics systemically may provide advantages to cancer patients because they express much lower levels of TGFβ, VEGFA, VEGFC, MMP-9, and MMP-1." (PMID 23667623, 2013). "In addition, some MMPs including MMP-1, MMP-2 and MMP-13 are involved in Wnt-5a mediated invasion of cancer cells." (PMID 21998657, 2011). "MMP-1 has been described in a wide range of advanced cancers with a significant negative correlation with survival." (PMID 21835023, 2011). "MMP-1 is also up-regulated in a wide variety of advanced cancers, and a significant negative correlation has been observed between its expression and patient survival." (PMID 21966428, 2011). "Our findings of an increased MMP-1 expression in EAC is well in line with results obtained in other cancer entities and few samples of EAC without clinicopathological association suggesting a putative role in invasion, metastasis and poorer survival." (PMID 20946664, 2010). "Similarly, E-cadherin has been reported to transcriptionally regulate a variety of integrins and matrix metalloproteases (MMP1, MMP2, MMP3, MMP14 and TIMP-1) in other cancer models." (PMID 19257890, 2009). "Furthermore, we demonstrated that the secreted MMP1 from fibroblasts was increased by those cancer cells without a high concentration of MMP1." (PMID 38320998, 2024). "The regulatory role of RKIP in MMP1 and MMP2 expression appears to be through RKIP’s inhibitory regulation of the NF-kB pathway, as inhibition of this pathway nearly fully inhibits the increased invasive capabilities observed in cultured cancer cells when RKIP is lost." (PMID 36765912, 2023). "However, the increased expression of GADD45B, ITGB5, MMP1, and BNDF was correlated with a decreased chemotherapy resistance of cancer cells to mithramycin, tramrtinib, ARRY-162, dabrafenib, selumetinib, vemurafenib, nilotinib, coimetinib, cyclophosphamide, oxaliplatin, and tamoxifen." (PMID 35699863, 2022).
cancer (continued). "Instead, we not only verified the tumorigenic role of RUNX2 in TNBC progression and cancer chemoresistance both in vitro and in vivo, but also revealed the regulatory mechanism of RUNX2 via directly targeting the specific binding site in the promoter region of MMP1." (PMID 36483054, 2022). "In contrast, infrared rays (IRs) do not seem to cause cancer, but they contribute significantly to skin aging, especially those in the IRA range (770–1400 nm) and increase the concentration of metalloproteinase-1 (MMP-1) in dermal fibroblasts of the matrix." (PMID 35482661, 2022). "However, systematic pan-cancer analysis about the prognostic and immunological roles of MMP1 has not been explored." (PMID 36727076, 2022). "Additionally, G-Rh1 suppressed the mRNA expression of RhoA, ROCK1, MMP1, and MMP9 in cancer cell." (PMID 36500403, 2022). "Furthermore, the formation of elongated BM-piercing actin protrusions in breast acini does not depend on cancer-related secreted MMP-1, -3, -7, -9 and cell membrane-bound (MT1-MMP)." (PMID 34440749, 2021). "MMP-1 is described in a variety of advanced cancers, and colon cancer is no exception." (PMID 34502094, 2021). "The results of meta-analyses suggest that polymorphisms in MMP-1, MMP-2, and MMP-7 may be associated with cancer risk in Asian or Latin-American populations, but not in European or Caucasian populations." (PMID 32765800, 2020). "Moreover, it has been shown that cancer exosomes could trigger MSC differentiation into pro-angiogenic and pro-invasive myofibroblasts, secreting high levels of matrix-regulating factors (MMP-1, -3, and -13), VEGF-A, and HGF." (PMID 32260433, 2020). "MMP1, a member of MMP in degrading the interstitial collagen types I, II, III, is constitutively expressed in normal physiologic conditions at a low level, while in pathologic conditions its expression may increase remarkably especially in cancer." (PMID 31244308, 2019). "In addition, cortactin has been shown to be crucial for trafficking the key invadopodia proteases, including matrix metalloproteinase 1 (MMP1), MMP2, and MMP9 from late endosomes to the plasma membrane, which play a crucial role in the invasive potential of cancer cells." (PMID 29152154, 2017). "Such factors, which include the collagenases MMP-1 and MMP-13 and the stromelysin MMP-3, have well documented roles in disease progression and can in particular aid cell penetration through extracellular matrices, supporting invasion and metastasis in several cancer types." (PMID 25596732, 2015). "In addition, SOD2 knockdown led to the down-regulation of MMP1 expression, in agreement with previous observations that SOD2-dependent production of H2O2 regulates expression of MMP family members (including MMP1) and contributes to cancer cell metastasis." (PMID 22408395, 2012). "Therefore, inhibition of the activity of PAR1 by directly targeting PAR1 itself, rather than MMP1, may be crucial to safely suppressing cancer-cell migration and invasion." (PMID 26392299, 2015). "However, carcinoma samples with MMP-11 positive MICs showed a more important increase in the mRNA level of 19 factors: IL-1, −5, −6, −8, −17 and −18, ADAM-8, −10, −15, and −23, ADAMTS-1, −2, and −15, IFNβ, MMP-1, as well as mediators related to inflammation (CCL-3, IRAK-4, MyD88 and NFκB)." (PMID 23145063, 2012). "Unlike its mechanism in cancer metastasis, we show that ENO promotes ECM production and reduces MMP-1 and MMP-3 levels and, thus, ECM degradation." (PMID 34935642, 2021). "Although Raf/MEK/ERK-mediated regulation of transcription factors is involved in the regulation of MMP13 by RKIP, it has been determined that this pathway is not required for the observed invasive nature of cancer cells with regards to RKIP and MMP1 and MMP2 in vitro." (PMID 36765912, 2023).
cancer (continued). "However, when comparing patients with benign pathologies and cancer, differences in MMP-1 and MMP-7 resulted not significant (Mann-Whitney U test, P = 0.448 for MMP-1 and P = 0.090 for MMP-7)." (PMID 28117344, 2017). "Our datasets suggest that in response to MIT‐mediated chemotherapy, cancer cells also become senescent, but they do not express a typical SASP, as the expression levels of a number of key SASP factors such as IL1α, IL6, CXCL8, and MMP1 remained largely unchanged." (PMID 40265973, 2025). "After adding 740Y-P, PI3K agonist, the expression of SBEM protein in cancer cells of miR-186-5p mimic + 740Y-P group was significantly decreased than the miR-186-5p mimic NC + 740Y-P group, while the protein levels of p-PI3K, p-AKT, MMP1, MMP3 and MMP9 were not significantly changed." (PMID 37477531, 2023).
infection (68 papers, 2009 to 2025). The state of being infected such as from the introduction of a foreign agent such as serum, vaccine, antigenic substance or organism. "The matrix metalloproteinase 1 (MMP1) gene which is involved in tissue repair gets downregulated by L. braziliensis causing lesions that facilitate the infection and ultimately lead to parasite survival." (PMID 36814446, 2023). "Elevated levels of MMPs (specifically MMP-1) were found associated with bacterial meningitis and were correlated with cerebral injury and infection severity during infection." (PMID 25408909, 2013). "To determine the relative effect of these additional vhs variants on vhs-induced mRNA degradation, RNA samples were harvested 15 hours after infection and analysed by RT-qPCR for two cellular transcripts we have previously shown to be highly susceptible to vhs degradation—MMP1 and MMP3." (PMID 37343008, 2023). "The infection caused upregulation of a set of MMPs (MMP1, 3, 9, and 12), and this finding could be validated in lung biopsies from patients with non-cavitary TB." (PMID 29259583, 2017). "Recently, we have tested whether endothelin-1 and MMP-1 act in the same molecular pathway in our mouse model of infection-associated preterm birth." (PMID 20706662, 2010). "Furthermore, knock-down of MMP-1 resulted in animals significantly more susceptible to infection by the entomopathogenic fungus Beauveria bassiana than control (RNAi) animals providing evidence for a direct role of MMP-1 in insect innate immunity." (PMID 19270735, 2009). "In the current study, PCMP-treated wounds showed significant upregulation of MMP-1, -2, -7, and -9 compared to controls, suggesting that the inherent processes of infection clearance, immune response activation, and tissue remodeling were active." (PMID 41009757, 2025). "In BAL at 5 weeks from infection, the same group displayed elevated levels of the pro-inflammatory cytokine IL-1β, and the matrix metalloproteinase-1 (MMP1), which remodels tissues." (PMID 41006234, 2025). "In the IL-17 signaling pathway, MMP1 is typically upregulated to help immune cells reach the infection site." (PMID 40005840, 2025). "The infection in the infected wounds was more intense, which was also demonstrated by the significantly increased expression of matrix metalloproteinase 1 (MMP‐1), especially on the 11th and 15th days." (PMID 39482270, 2025). "In our study, we found a high MMP-1 level that indicated a high ongoing infection process, as indicated by BTA, culture, PCR, and histological findings." (PMID 36743515, 2023). "Mφ are major sources of MMP-1, infection and inflammation increased MMP-1 secretion in lung tissues, indicating MMP-1 is an important driver for lung immunopathology." (PMID 37766868, 2023). "Although transient upregulation in multiple matrix metalloproteinase (MMP) transcripts was reported previously during toxin-induced intestinal inflammation in mice, we see only MMP1 modulated over time in early infection." (PMID 37615437, 2023). "Extracellular lactate above 10mM; which occurs in meningeal, pleural and peritoneal TB, also increased MMP-1 secretion in the presence of infection." (PMID 37418488, 2023). "Generally, the rabbits administered with the higher doxycycline dose showed better results in terms of a lower infection progress and lower MMP-1 levels." (PMID 36743515, 2023). "We observed the course of infection through the blood concentration changes and immunohistochemical examination of MMP-1, in addition to BTA staining, culture, polymerase chain reaction (PCR), and histopathological examination." (PMID 36743515, 2023). "At weeks 5 and 9 of infection, a significant increase in MMP-1 and MMP-9 expression was observed in the lungs of infected mice compared to uninfected control mice." (PMID 36293113, 2022). "The WB results demonstrated that infection of siMMP1 lentivirus can decrease the expression of MMP1." (PMID 35426219, 2022).
infection (continued). "During primary infection, we found that MMP1 was increased in PBMCs, which can promote and maintain the latent cycle." (PMID 36272970, 2022). "We inhibited Mmp1 activity specifically in EEs by overexpression of its inhibitor, TIMP, or by depletion of Mmp1, and observed a drastic reduction of protrusion formation and migratory ability of ISCs after Ecc15 infection." (PMID 34887411, 2021). "Nevertheless, the loss of COL6A2, MMP1, and MMP3 transcription in WT infection compared to Δvhs infection was considerably greater (8- to 15-fold), thereby confirming their vhs-dependent transcriptional downregulation." (PMID 33148793, 2021). "Infection with Mycobacterium tuberculosis causes cellular injury by increasing the production of MMP-10, MMP-1, and MMP-7 in macrophages." (PMID 34944659, 2021). "Previous studies also demonstrated a strong interaction of plasminogen with the cell surface of pathogens during infection and the role of plasmin in activation of matrix metalloproteases MMP-1 and MMP-9." (PMID 33803235, 2021). "Wildtype mice do not express the ortholog of MMP-1 in lung and do not develop caseous necrosis or cavities in response to Mtb; in human MMP-1 transgenic mice, however, infection with TB leads to collagen destruction and caseous necrosis." (PMID 30425706, 2018). "MMP-1 upregulation, as a result of epigenetic control, has the potential to drive tissue damage in the lung, thereby facilitating spread of infection and development of pathology." (PMID 28596772, 2017). "Hypoxia significantly increased MMP-1 gene expression in M.tb-infected human MDMs compared with infection in normoxia (21% pO2), resulting in a 170-fold increase in MMP-1 mRNA accumulation at 24 h (p<0.0001 by Kruskal–Wallis test)." (PMID 27245780, 2016). "For example, the expression of CFI, CXCR6, LGALS15, and MMP1 was significantly upregulated while TFF2 mRNA level was significantly repressed by infection only in the resistant breed (CHB), in a good agreement with the RNAseq analysis." (PMID 27197554, 2016). "Positive associations between MMPs and A. fumigatus have been reported previously in a study involving conidial infection of corneas, and MMP1 expression has been shown to be higher in sputum cells of asthmatics relative to controls." (PMID 20525375, 2010). "In response to P. aeruginosa, genes associated with IFN-γ response to infection (CXCL10, IL-24, IFNγR2) and other mediators of anti-infectious responses (CSF2, MMP1, MMP3, TLR2, S100 calcium-binding proteins A) were markedly up-regulated in wild-type TG cells." (PMID 19399182, 2009). "Furthermore, increased fold change in the chemokines ENA‐78 (P = 0.0226), fractalkine (P = 0.0052) and MCP‐2 (P = 0.0011) and growth factors HGF (P = 0.0197) and MMP‐1 (P = 0.0407) were also correlated with subsequent infection." (PMID 40766049, 2025). "The protein expression of seven proteins (CD8A, ST1A1, AXIN1, FGF-5, MMP-10, HGF, SIRT2) was significantly decreased and the protein expression of two proteins (MMP-1, TNFRSF9) was significantly increased in caspase-1-deficient cells compared to Cas9 cells following HK1651 infection." (PMID 40137780, 2025). "The notion of MMP1/PAR1 axis was initially demonstrated in the process of infection." (PMID 34753916, 2021). "Similarly, MMP1 mRNA expression was also enhanced in all cell lines tested 24 h after polymicrobial infection." (PMID 33391626, 2020). "MMP-1 may destabilize granuloma formation and promote tissue damage and disease progression early in the infection." (PMID 20111728, 2010). "Infection with HTLV-1A/CoI-L resulted in low overall frequency of monocytes, DCs, and neutrophils producing IL-10, with elevated frequencies of those producing TNF-α in both compartments, linked to high expression of IL-6, CCL2, and IL-33 in blood and of MMP1, IL-1β, CCL3, and CCL19 in the lung." (PMID 41006234, 2025).